TNF (tumor necrosis factor)
Diseases named in the same sentence as TNF in open-access papers (continued):
Sharing a sentence is not in itself a finding about the gene and the disease.
infection (continued). "Chronic low‐grade inflammation, particularly elevated tumor necrosis factor (TNF) levels, occurs due to advanced age and is associated with greater susceptibility to infection." (PMID 38459711, 2024). "The expression of IL-32 is upregulated by several cytokines, including TNF and IL-1β, as well as by infection, pathogen-associated molecular patterns (PAMPs) and oxidative stress." (PMID 37686029, 2023). "TNF-α facilitates macrophages to phagocytose and kill mycobacteria and is important in containing infection, reflected by the increased risk of TB in individuals receiving anti-TNF-α treatments." (PMID 38089636, 2023). "Patients with rheumatological diseases and AS that used immunosuppressive drugs, including anti‐TNF therapy, are considered to potentially be at a higher risk for infections and their complications." (PMID 37382255, 2023). "They estimated the relative risk for infection to 2.7 in infants whose mothers were treated with a combotherapy (anti-TNF agent and thiopurine), compared with anti-TNF monotherapy (95% CI, 1.09–6.78; p = 0.02)." (PMID 38068547, 2023). "Inhibition of TNF reportedly carries a risk of inducing a variety of infections in animal models and also in RA patients, as TNF α plays an important role in host immunity." (PMID 38013343, 2023). "Previously the IFN-I blockade infection model was used to establish an important role for cytoplasmic pathogenic sensing and TNF-α signaling during CCHFV-mediated pathogenesis." (PMID 37459918, 2023). "Macrophages acquire a pro-inflammatory M1 phenotype under the action of various infection- and damage-associated factors, such as LPS, TNFα, and IFNγ." (PMID 38069411, 2023). "IL-10 is an anti-inflammatory cytokine, ameliorating the excessive Th1 and CD8+ T cell responses (typified by overproduction of IFN-γ and TNF-α) that are responsible for much of the immunopathology associated with infections." (PMID 36828505, 2023). "As in our evidence synthesis, some expressed worry and fear about anti-TNF side effects (specifically increased infection risk) and symptom recurrence." (PMID 37608395, 2023). "In chronic stress, early trauma, and acute inflammation caused by infection, the expression of IL-6, a proinflammatory biomarker, is increased along with various putative biomarkers of inflammation, including TNF-α and CRP106." (PMID 36599852, 2023). "TNF-α release was significantly lower upon infection of neutrophils with PPAD-deficient than with WT P. gingivalis." (PMID 37629104, 2023). "Recently, in a zebrafish infection model, the rough morphotype caused inflammation by modulating host TNF-α signaling, leading to necrotic granuloma formation that was comparatively less accelerated in smooth morphotypes." (PMID 37200238, 2023). "This study shows that the risk of serious infections with anti-TNF-alpha was increased in the first six months of initiating therapy for RA, but gradually declined after a span of 24-36 months." (PMID 36606106, 2023). "Innate cytokines TNFα and IL-1β also showed some association with prior exposure by natural infection, consistent with previous results, but elevation was more marginal and restricted to specific subgroups of pre-exposed individuals." (PMID 37885896, 2023). "Predisposition to high-intensity infection is also seen in applying TNF inhibitors and IFNγ-targeted biologic emapalumab." (PMID 38143753, 2023). "One study showed that frailty, when present pretreatment, was associated with an increased risk of infections (19% vs. 9% for anti-TNF and 17% vs. 7% for immunomodulators, P < 0.01 in both groups)." (PMID 37674503, 2023). "Proteomic results showed that pathways of TLR, TCR, TNF, cancer and chemokine were significantly enriched on the 3rd day of infection, all of which were associated with upregulation of Ikbkg." (PMID 37587524, 2023). "The levels of IFN-γ, IL-12, as well as TNF-α, were decreased in the post-infection phase in MIF-deficient mice compared with control mice." (PMID 38275363, 2023).
infection (continued). "For older UC patients, the risk of mortality and serious infections was similar in steroid or anti-TNF-treated patients." (PMID 37443755, 2023). "AhR deficiency in mice revealed increased production of pro-inflammatory cytokines (e.g., IL-6 and TNF-α) by macrophages after infection, resulting in higher susceptibility to L. monocytogenes, with higher morbidity and mortality rates." (PMID 36672703, 2023). "The results showed that while wild-type PAO1 stimulated TNFα secretion from corneal epithelial cells, higher levels were detected after infection with the ∆exoSTY mutant, and the ∆exsA mutant causing an intermediate response." (PMID 37589460, 2023). "The infection causes macrophages to produce pro-inflammatory cytokines such as interleukin-1β (IL-1β), IL-12, IL-18, tumor necrosis factor-α (TNF-α), and interferon-α/β (IFN-α/β), all of which lead to cell damage during SAKI." (PMID 36769749, 2023). "TNF-α promotes the body’s ability to resist infection by pathogenic microorganisms and promoting mucosal immune protection." (PMID 38273828, 2023). "Cytokine levels of IFN-γ and TNF-α, which are associated with Th1-like inflammation, are almost the same in the infected groups 4 days after infection." (PMID 38133315, 2023). "The researchers discovered that leucine supplementation increased the synthesis of interferon-gamma (IFN-), interleukin-2 (IL-2), and tumor necrosis factor-alpha (TNF-), all of which are cytokines linked with improved immune function and infection protection." (PMID 38046946, 2023). "Expanding on these findings, we show that chronic (in vivo) manipulation of the signaling network via systemic administration of a TNF neutralizing antibody is sufficient to mitigate the hyperexcitability phenotype caused by infection." (PMID 38115011, 2023). "This is an important issue because the reduced production of inflammatory factors, particularly IL-8 and TNF-α, is associated with a less serious infection and ensuing sequels." (PMID 36979076, 2023). "A recent systematic review and meta-analysis including randomized clinical trials investigated the infection risk of available biological drugs in CD (anti-TNF agents, vedolizumab and ustekinumab)." (PMID 37176535, 2023). "Other pathways linked to infection and host cell associations such as adherens junctions, endocytosis, TNF signaling, lysosome, and TGF-β signaling pathways were also identified." (PMID 37569480, 2023). "The cytokine patterns of the athletes revealed that athletes have an elevated immune status even 4–6 weeks after the infection and that it is either a general TNF-alpha-related response or a cellular immune response associated with IFN-gamma." (PMID 37234053, 2023). "The profile of severe infection was correlated with the decreased polarization to the M1 phenotype due to TNF deficiency and increased M2 phenotype." (PMID 37235324, 2023). "Dysregulation of pro-inflammatory cytokines (TNF-α, IL-1β and IL-6) and anti-inflammatory cytokines (IL-10) are often associated with life-threatening infection or presence of endotoxin." (PMID 37424774, 2023). "A meta-analysis of randomized placebo-controlled trials showed a risk of serious infection between 0 and 2.9% in patients with SpA exposed to anti-TNF." (PMID 38076262, 2023). "Upon infection, S. aureus induces the expression of genes encoding pro-inflammatory cytokines, including IL-6, IL-1β, and TNF-α." (PMID 37759998, 2023). "Anti-TNF use in older persons with IBD has been associated with serious infections (aHR: 3.92; 95% CI: 1.185, 12.973), when adjusting for age at diagnosis and number of comorbidities." (PMID 37674503, 2023). "Th1‐like immune response involves cytokines such as IFN‐γ, IL‐2, and TNF‐α, which are associated with controlling the infection and mild to moderate disease in dogs." (PMID 38053473, 2023). "Hyperexcitability of CA1 pyramidal neurons caused by infection was mitigated via an anti-TNF antibody and genetic silencing of FGF14 in CA1." (PMID 38115011, 2023).
infection (continued). "Of these, interleukin-6 receptor inhibitors, used only in RA, pose a higher risk of serious infection than tumor necrosis factor inhibitors, commonly used throughout all IMIDs." (PMID 37409280, 2023). "In patients who will be treated with TNF-α inhibitors, a careful preliminary assessment of the presence of latent tuberculosis is mandatory, since there is a high risk of reactivation of the infection with these drugs." (PMID 37113615, 2023). "Other pathways linked with infection and host-cell associations, such as adherens junctions, endocytosis, TNF signaling, lysosome- and TGF (transforming growth factor)-β signaling pathways, were also identified." (PMID 36768651, 2023). "In cotyledons, genes associated with the IFN response, TNF-alpha signalling via NF-κB, complement and coagulation were only stimulated by the high-virulence isolate at the earliest stage of infection." (PMID 37520552, 2023). "At the same time, a large of pro-inflammatory cytokines (interleukin-6, C-reactive protein, tumor necrosis factor-α, etc.)are synthesized and secreted upon pathogenic infection." (PMID 38223568, 2023). "Increased levels of IL-1, IL-6 and TNF are often detected in several tissues during acute ASFV infections and associated with lymphoid depletion, hemorrhages and oedemas." (PMID 36680273, 2023). "The increased IFN-I induction observed in response to infection with the MAB-R variant was associated with a corresponding increase in TNF-α and intracellular death induced by enhanced macrophage nitric oxide production." (PMID 36674717, 2023). "Studies show that host cells infected with C. trachomatis release pro-inflammatory cytokines throughout their growth cycle, which together with IL-1b, TNF, and IL-10, are associated with poorer prognosis of the infection." (PMID 36897879, 2023). "Children born to mothers treated during pregnancy with a combination of thiopurine and anti-TNF had an increased risk of serious infection during the first year of life." (PMID 36836832, 2023). "Infants whose mothers received a combination of an anti-TNF agent and thiopurine had a 2.7-fold higher risk of infection compared with those treated with an anti-TNF monotherapy (95% CI, 1.09–6.78; p = 0.02)." (PMID 38068547, 2023). "qPCR and Multiplex immunoassay performed in lung homogenates confirmed that, in line with cytospin analysis, infection at ZT12 was associated with lower levels of expression of pro-inflammatory cytokines TNFα, IL-6, and IL-1β and the chemokine CXCL1." (PMID 36896128, 2023). "WHO-VigiAccess and FAERS, as the databases to evaluate post-marketing drug vigilance, showed differences in the types and incidence of infection-related adverse reactions caused by anti-TNFα agents." (PMID 37554981, 2023). "Only infection with HPV-35 was associated with significantly higher concentrations of TNF-α after adjusting for BV status." (PMID 36992467, 2023). "TNF-α is a proinflammatory cytokine secreted by macrophages in response to cell damage caused by infection and regulates cell functions including proliferation, survival, differentiation, and apoptosis." (PMID 36828505, 2023). "In contrast, patients susceptible to repeat infections (≥3) had an average IL-10:TNF-α ratio of 14.9." (PMID 37180165, 2023). "Pro-inflammatory cytokines, such as IL-1α, TNF-α, and IL-6 have also been linked to lymphoid hyperplasia in the initial stages of the infection." (PMID 36766408, 2023). "As TNFα plays a vital role in defense mechanisms against infections, TNFis increase the risk of infection, including TB." (PMID 36909171, 2023). "CXCL8 acts to recruit immune cells to the site of infection and has an important role in neovascularization, while TNFα is important to induce acute inflammation and is implicated in neutrophil survival/apoptosis." (PMID 36768864, 2023). "Data are mainly available for anti-TNF therapy, where the infection risk seems to decline over time." (PMID 36389682, 2022).
infection (continued). "In this section the mechanisms by which TNF inhibitors and other immunomodulators predispose or protect individuals from infection by select respiratory pathogens will be explored." (PMID 36159650, 2022). "S. aureus USA300 infection caused overexpression of IL‐6, TNF‐α, and IL‐1β in serum, resulted in microglial over‐activation and excessive release of proinflammatory cytokines in the mPFC." (PMID 35977050, 2022). "Biological agents, especially anti-tumor necrosis factor-α (TNF-α) monoclonal antibodies, have been reported to be effective in some refractory cases; however, they are limited to patients at high risk of infection." (PMID 35255957, 2022). "Cumulatively, the increase in the need for TNF inhibitors and increased globalization will produce a setting where TNF inhibitor-associated infections is a growing issue that must be addressed." (PMID 36159650, 2022). "Microglia are the first defense mechanism, acting as a responder against inflammation, infection, and injury by producing inflammatory cytokines, including TNF-α and IL-6 associated with chemokines." (PMID 36704003, 2022). "IL-2, IL-5, IL-17F, IFNγ and TNFα inductions were positively associated with the infection status in the N-peptides restimulated cells (308%, 65%, 39%, 304% and 40% increase when infected, respectively, FDR < 0.1)." (PMID 35313592, 2022). "SARS-CoV-2 D614G- and Delta- variant infection induced production of inflammatory cytokines, including high-level of IL-2, GM-CSF, KC at day 3 pi and IL-1β, TNF-α, IL-2, IL-4, IL-6, KC (Neutrophil chemoattractant) at day 7 pi." (PMID 35734088, 2022). "This review will outline the mechanism of immune modulation caused by TNF inhibitors and how they predispose to infection with a focus on Mycobacterium tuberculosis, Legionella pneumophila, and Pneumocystis jirovecii." (PMID 36159650, 2022). "In the early lung infection mouse model, the TNF response to ply‐deficient S. pneumoniae was enhanced and bacterial clearance increased compared to infection with wild‐type S. pneumoniae." (PMID 35835695, 2022). "It was reported that mice with intact IFN-γ but a deficiency in IL-6 and TNF-α all succumbed to MTB after infection." (PMID 35265079, 2022). "Meanwhile, the mRNA expression level of proinflammatory cytokines, IL-1β, IL-6, and TNF-α were remarkably reduced at 12–24 hpi after PR8 infection, which showed a high association with the decrease in β-TrCP." (PMID 36366524, 2022). "The specific process of NCPS involves activation of RIP1 by TNF-α/TNFR1 when caspase-8 is cleared or inhibited by mutation or infection and the subsequent recruitment of RIP3 through the RIP homotypic interaction motif (RHIM)." (PMID 35892430, 2022). "In contrast to ustekinumab and vedolizumab, anti‐TNF therapy is known to be associated with an increased risk of serious infection, defined as infection requiring hospitalisation." (PMID 35301734, 2022). "The focA mutation led to increases in IL-12 and TNF-α, indicating that the FocA protein plays a role during infection in suppressing these early indicators of the immune response." (PMID 36013975, 2022). "Pro-inflammatory cytokines such as the TNF-α and IL-1β have been shown to mediate host immune function and produce an immune response quickly after pathogenic microorganisms infection." (PMID 35236420, 2022). "The increased risk for infection for patients on combination therapy shown in our study support that IM and anti-TNF therapy should be carefully controlled in patients with IBD." (PMID 35140875, 2022). "Consistently elevated cytokines included pro-inflammatory interleukin (IL)-6 and tumor necrosis factor (TNF)-α, both of which are associated with classical innate immune activation and play a critical role in acute phase response during early infection." (PMID 36463221, 2022).
infection (continued). "We found that FXR deficiency in hepatocytes promoted the progression of liver injury, aggravated weight loss and death caused by infection, and promoted inflammatory cytokines production, such as IL-6, IL-1β, TNF-α, IL-4, IL-10, and IL-13." (PMID 35930537, 2022). "Excessive TNF can cause tissue damage, which is one of the core cytokines of an “inflammatory storm” caused by infection." (PMID 35818408, 2022). "We found that the skin lesion in diabetic rats was susceptible to infection due to the wound exposure, and the levels of TNF-α, IL-1β and IL-6 in wound tissues were significantly increased on day 7 after surgery." (PMID 35130118, 2022). "Higher levels of cytokines such as TNFα and IL-17 in the early stages of infection have been linked to worsening of the disease and tissue injury." (PMID 36238303, 2022). "Massive unregulated release of pro-inflammatory cytokines (cytokine storm) such as tumor necrosis factor-alpha (TNF-α) and interleukin-6 (IL-6) due to infection, nerve injury or immunotherapy causes organ damage and unbearable pain." (PMID 35806192, 2022). "This fact raised major concerns about the long-term impact of in utero exposure to anti-TNFα on the neonatal immune system and risk of infections." (PMID 36120653, 2022). "A meta‐analysis of RCTs in AS found low risk of serious infection (4 per 1000 patient‐years) on anti‐TNF drugs compared with placebo." (PMID 35478442, 2022). "Data using the ECM model of CM concurs with this finding whereby infection of TNF-α deficient mice still die from BBB breakdown in the same time frame as intact animals." (PMID 36146602, 2022). "Degradation of RIP1 resulted from elevated expression of Ctsb in HDAC3 deficient macrophages impaired TNFα mediated NF-κB activation and eventually impaired the inflammatory response and anti-infection immunity of host." (PMID 35658939, 2022). "The pathways which were associated with infection and host cell responses included endocytosis, focal adhesion, chemokine signaling pathway, Hippo signaling pathway, TNF signaling pathway, TGF-β signaling pathway, and adherens junctions." (PMID 36093177, 2022). "VDZ seems to be associated with less serious infections than anti-TNF, at least in some studies, with others showing similar data." (PMID 35160280, 2022). "The risk of serious infection was comparable between tocilizumab users and TNF inhibitor users (HR = 1.05, 95% CI 0.95–1.16)." (PMID 36430392, 2022). "Infection caused due to bacteria blocked FoxO3 and over-stimulated cytokine production in the epithelial cells of intestine, whereas TNF-α-induced FoxO3 inactivation boosted IL-8 in HT-29 cells." (PMID 35156517, 2022). "Patients with IBD had an increased risk of infection due to immune system dysregulation associated with the use of corticosteroids, immunosuppressant drugs, and anti‐ tumor necrosis factor (TNF)α." (PMID 35634190, 2022). "For instance, infection by Salmonella, through TNF-α mediated inflammation, can cause the decrease of circulation IgG titers to a previously immunizing antigen, by mobilizing LLPCs from the bone marrow without replenishment of the lost population." (PMID 35669785, 2022). "Studies utilizing animals with genetic mutations in the TNF pathway observed increased susceptibility to infection, and cell culture of lung epithelial cells with influenza virus showed a dose-dependent response in the production of TNF-α." (PMID 36297092, 2022). "Host immune cells release cytokines such as TNF-α, IL-6, and IL-12 that cause inflammatory signals which recruit more effector cells such as macrophages, neutrophils etc. to site of infection, thereby clearing the pathogen." (PMID 35813825, 2022). "Through the analysis of a health insurance database, it was demonstrated that subcutaneously administered anti-TNFs exhibited a higher risk of serious infections (HR, 1.34; 95% CI, 1.18–1.53) than intravenous anti-TNF." (PMID 35644668, 2022).